VWF (von Willebrand factor)
Diseases named in the same sentence as VWF in open-access papers (continued):
Sharing a sentence is not in itself a finding about the gene and the disease.
liver disease (continued). "Increased levels of Factor VIII (FVIII) and VWF have also been observed in cirrhotic patients with portal hypertension, suggesting that a procoagulant milieu may prevail." (PMID 37443746, 2023). "Other proteases, including plasmin or elastase, can also break down vWF in liver disease." (PMID 36837547, 2023). "Hepatic cell necrosis, subsequent liver regeneration, and/or high shear stress due to portal hypertension in cirrhotic livers may play major roles in upregulating VWF in the hepatic sinusoidal endothelium." (PMID 38003518, 2023). "Thrombocytopenia, in turn, may be partially compensated by increased VWF, which is commonly raised in liver disease." (PMID 37546051, 2023). "Recent studies have shown that elevated VWF levels indeed correlate with increased portal pressure, and might even serve as a non‐invasive marker of portal hypertension." (PMID 35446468, 2022). "In addition, as a noninvasive biomarker, VWF can predict portal hypertension and esophageal varices in patients with HBV infection and cirrhosis." (PMID 36002595, 2022). "Because the hemodynamic effects of portal hypertension (PHT) can induce hepatic encephalopathy, HRS, and ascites, it is possible that ADAMTS13:AC and VWF:Ag are associated with these conditions through Et-induced development of hepatic encephalopathy, HRS, ascites, and subsequent PHT." (PMID 35407443, 2022). "These VETs may, therefore, substantially underestimate the haemostatic status in patients with liver disease, in which changes in protein C and VWF are frequently observed." (PMID 35446468, 2022). "The results showed that the serum vWF in the cirrhosis group with portal hypertension was significantly higher than that in the non-portal hypertension group, with a comprehensive sensitivity of 0.823 (95% CI:0.788, 0.855) and a binding specificity of 0.782 (95% CI:0.708, 0.845)." (PMID 36186776, 2022). "Furthermore, it is becoming increasingly clear that patients with liver disease have hypercoagulable components in their hemostatic status [e.g., increases in von Willebrand factor (vWF), factor VIII, and decreases in anticoagulant proteins]." (PMID 35518552, 2022). "As von-Willebrand factor is known as non-invasive predictor for portal hypertension, hepatic decompensation and a marker for procoagulant imbalance, this significant elevation in ACLF patients maybe represents more severe illness in this cohort." (PMID 32807080, 2020). "Importantly, we also investigated parameters associated with factor VIII levels: VWF and factor VIII levels showed a correlation of moderate strength, which seemed to be comparable throughout groups/strata of hepatic dysfunction/portal hypertension severity." (PMID 32052552, 2020). "Apart from portal hypertension, several other factors influencing VWF levels have been identified." (PMID 32052552, 2020). "Based on our previous study of patients with SOS after SCT, we hypothesize that the second mechanism is related to VWF-rich platelet thrombosis in sinusoids, which induces portal hypertension and splenomegaly." (PMID 26580395, 2015). "Significantly, CMCS treatment could inhibit the expression of vWF with increased level, which might be an original finding in the liver disease and the study of its mechanism." (PMID 24442316, 2014). "Further, vWF levels were shown to correlate with the degree of portal hypertension as measured by hepatic venous pressure gradient and vWF levels were predictive of survival free of portal hypertension-related events and liver transplantation." (PMID 25397410, 2014). "Elevated VWF titer in cirrhosis may result from endotoxemia due to bacterial translocation and shear stress induced by hyperdynamic splanchnic circulation (portal hypertension), both of which may promote conformational changes in VWF that enhance its affinity for platelet binding." (PMID 40764410, 2025).
liver disease (continued). "Liver disease may disrupt pro- and anti-haemostatic factors that involve components of primary haemostasis (platelets, fibrinogen and von Willebrand factor (VWF)), secondary haemostasis (coagulation proteins), and fibrinolysis, resulting in a state of abnormal but “re-balanced haemostasis”." (PMID 37546051, 2023). "Since the ADAMTS-13 to VWF ratio (ADAMTS-13/VWF) and FVIII to PC ratio (FVIII/PC) are linked to alterations that occur during liver decompensation or are associated with complications related to portal hypertension, their role as predictive biomarkers has been postulated in several studies." (PMID 37443746, 2023). "Research has shown that patients with liver disease, especially those with autoimmune hepatitis, demonstrate decreased ADAMTS13 activity and elevated VWF levels; thus, ADAMTS13 is a reliable indicator of liver synthetic function." (PMID 40725629, 2025). "Plasma VWF titers have statistically positive correlations with TSB, DSB, AST, ALT, liver span, portal hypertension, MELD, PELD, Child–Pugh scores, APRI (AST to Platelet Ratio Index), and FIB-4 (Fibrosis-4) scores (P < 0.05)." (PMID 40764410, 2025). "Other studies suggested that patient selection has a relevant effect on the relation between liver disease severity, ADAMTS13-Act, and VWF multimer size." (PMID 37605068, 2023). "Patient blood type, age, sex, smoking status, coffee consumption, comorbidities (such as DM and liver disease), and use of HMG-CoA reductase inhibitor or heparin usage can also affect vWF characteristics." (PMID 37746066, 2023). "Both vWF and ET-1 were markedly elevated before OLT, correlating significantly with severity of liver disease (MELD and variceal staging) and decreased substantially when rechecked 6 weeks after transplantation." (PMID 33080821, 2020). "ADAMTS13:AC decreases with increasing severity of liver disease, leading the observed imbalance between the decreased ADAMTS13:AC and the increased VWF:Ag in cirrhotic patients." (PMID 31638892, 2019). "This is not due to an increased synthesis of FVIII, but rather the increased endothelial production and release of von Willebrand Factor (vWF), which binds FVIII thereby increasing its half-life, and whose expression is correlated with portal hypertension and liver failure." (PMID 36894870, 2023). "In line, changes in non-invasive surrogates of portal hypertension (LSM/VWF/VITRO) were comparable between carriers and non-carriers of the PNPLA3 G-allele in the overall cohort." (PMID 33917196, 2021). "Stratification by severity of hepatic dysfunction/portal hypertension revealed, that the impact of ABO blood type on VWF (and possibly, factor VIII) levels seemed to be limited to ACLD patients with less advanced disease (ie, patients with CTP A, subclinical portal hypertension, or MELD <10 points)." (PMID 32052552, 2020). "Moreover, hepatic individuals with portal hypertension and esophageal varices had a considerably higher VWF Ag titer than those without these conditions (P < 0.05)." (PMID 40764410, 2025). "In this study, we assessed VWF and ADAMTS13 parameters, cVWF levels, and markers of fibrinolytic activity in patients with acute and chronic liver disease across varying disease severities, as well as in patients with sepsis without underlying liver disease." (PMID 41035784, 2025). "However, in advanced stages of liver fibrosis, endothelial cells of hepatic sinusoids acquire the phenotype of vascular endothelium due to chronic inflammation and endotoxemia, which are the main contributors to portal hypertension, and begin to produce FVIII and VWF." (PMID 37443746, 2023). "However, TEG has its limitation and is likely to underestimate the hemostatic potential in liver disease, as it does not account for von Willebrand factor and protein C levels." (PMID 37600623, 2023).
liver disease (continued). "However, as a result of the limited sample size in some of the groups/strata, we cannot entirely rule out that liver disease severity modulates the correlation between VWF and factor VIII levels." (PMID 32052552, 2020). "Yet, it remains unclear whether there is physiological connection between increased vWF and decrease platelet count or not, but most interestingly both changes are commonly found in portal hypertension." (PMID 25397410, 2014). "We compared the dynamics of surrogates in portal hypertension (PLT, LSM, VWF, and VITRO score) between patients with or without the PNPLA3 rs738409 G-allele in the overall study population." (PMID 33917196, 2021).
Cirrhosis (46 papers, 2011 to 2026). A chronic disorder of the liver in which liver tissue becomes scarred and is partially replaced by regenerative nodules and fibrotic tissue resulting in loss of liver function. "Plasmin, the central effector of fibrinolysis, has been implicated in VWF proteolysis in cirrhosis, based on the identification of plasmin-generated cleavage fragments in patient plasma." (PMID 41035784, 2025). "vWF is secreted from endothelial cells, and circulating levels of vWF predicted mortality and risk of decompensation in patients with cirrhosis." (PMID 34572384, 2021). "Hepatocellular carcinoma in patients with cirrhosis is associated with increased platelet aggregation and higher levels of platelet adhesive glycoprotein von Willebrand factor." (PMID 33800224, 2021). "On the other hand, the increase of von Willebrand factor and other procoagulants, as well as the decrease in generation of antithrombin in patients with cirrhosis, could cause an imbalance in the coagulation and fibrinolytic systems." (PMID 37794517, 2023). "Moreover, vWf+ LSECs were significantly correlated to the fibrosis stage in patients with cirrhosis and a higher vWF expression has been linked to old age and pseudocapilarization." (PMID 34746184, 2021). "Indeed, von Willebrand factor (VWF) antigen levels are markedly elevated in patients with both acute liver injury and acute liver failure syndromes and in advanced chronic liver disease defined by underlying cirrhosis, and they increase with disease severity." (PMID 41035784, 2025). "In conclusion, in a prospective study in patients with cirrhosis, we demonstrate that hepatocellular carcinoma is associated with significant changes in primary hemostasis that include increased platelet aggregation and higher levels of plasmatic von Willebrand factor." (PMID 33800224, 2021). "Levels of vWF are elevated in cirrhosis, which may be due to different causes." (PMID 25397410, 2014). "Although platelet count is reduced in cirrhosis, platelet function is enhanced due to compensation by the highly active von Willebrand factor." (PMID 40385847, 2025). "IL-6, CD163, and vWF were higher (p <0.01) at baseline in patients with cirrhosis and CSPH compared to those with subclinical PH and controls." (PMID 39850960, 2025). "The authors came to the conclusion that, in situations of chronic hepatitis C infection, VWF offers a straightforward yet useful method for grading liver fibrosis and detecting undetectable cirrhosis." (PMID 40764410, 2025). "It has been shown that vWF correlates with the extent of portal hypertension and because of that it gradually rises in subjects with compensated cirrhosis and even more in decompensated cirrhosis." (PMID 38396688, 2024). "A previous study reported that ADAMTS13 activity (ADAMTS13:AC) and VWF antigen (VWF:Ag) are predictive biomarkers of ACLF development in patients with cirrhosis." (PMID 36829443, 2023). "In cirrhosis, endothelial dysfunction has been inferred through different studies that show an upregulation of markers such as P-selectin, vWF, and isoprostanes in systemic venous blood." (PMID 35160251, 2022). "Increased vWF in the plasma of patients with acute liver failure and cirrhosis suggests poor prognosis." (PMID 32347385, 2020). "Accordingly, it is unclear if, and to what extent, ABO blood type impacts on VWF/factor VIII levels in patients with cirrhosis." (PMID 32052552, 2020). "In thrombocytopenic (<150/nL) patients with cirrhosis, normal PFA-100 results were associated with higher vWF-antigen levels (462.3±235.9% vs. 338.7±151.6%, P = 0.021)." (PMID 25397410, 2014). "Decrease in platelet function in cirrhosis is compensated by high plasma levels of VWF which compensates for platelet capacity to provide surface for thrombin generation." (PMID 22164337, 2011). "In patients with cirrhosis, VWF plays a key role together with factor IX and negatively charged phospholipids of activated platelets to boost thrombin generation." (PMID 22164337, 2011).
Cirrhosis (continued). "In particular, the dynamic changes in vWF and ADAMTS13 levels across advancing stages of cirrhosis could serve as early indicators of ACLF risk, offering a potential tool for identifying patients who may benefit from closer monitoring." (PMID 40429533, 2025). "Both ROTEM and TEG have limited sensitivity to elevated vWF levels and decreased protein C levels, both of which compensate for the lower platelet count and decreased levels of procoagulant factors in decompensated cirrhosis." (PMID 40429533, 2025). "However, when corrected for total VWF:Ag, ADAMTS13-cleaved VWF was increased in patients with stable cirrhosis but was comparable to controls in the other patient groups." (PMID 41035784, 2025). "The VWF:Ag/ADAMTS13:AC predicted prognosis in patients with cirrhosis with ACLF." (PMID 36829443, 2023). "The mechanism responsible for the decrease in ADAMTS13:AC in patients with advanced cirrhosis may include enhanced consumption due to the degradation of large quantities of VWF, inflammatory cytokines, and/or ADAMTS13 plasma inhibitors." (PMID 38003518, 2023). "In patients with cirrhosis, HCC is associated with increased platelet aggregation and higher VWF." (PMID 33800224, 2021). "Patients with cirrhosis have profound alterations of primary hemostasis that include low platelet count, increased levels of Von Willebrand factor (VWF), and complex alterations of platelet function, which makes platelet assessment in these patients more challenging." (PMID 33800224, 2021). "As a result, cirrhosis may even be considered as a prothrombotic condition, with thrombophilic changes such as elevated VWF/factor VIII levels potentially contributing to the high risk of thrombotic events." (PMID 32052552, 2020). "Moreover, the cirrhotic liver cannot clear von Willebrand Factor (vWF) which further adds to the prothrombotic effects of cirrhosis." (PMID 30792971, 2019). "Effect of vWF levels on primary hemostasis in thrombocytopenic patients with cirrhosis." (PMID 25397410, 2014). "Our findings revealed that VWF may be a predictor of cirrhosis." (PMID 36002595, 2022). "Moreover, some evidence links VWF/factor VIII levels with incident PVT in patients with cirrhosis." (PMID 32052552, 2020). "In patients with decompensated cirrhosis, ultra-large vWF multimers promote platelet aggregation and PVT, linking vWF to tumor progression via vascular and microthrombotic mechanisms." (PMID 41228207, 2025). "Similar observations have been made in cirrhosis, where high collagen-binding activity was observed despite a relatively low ratio of collagen binding to total antigen, indicating that collagen-binding assays may overestimate VWF function when multimeric structure is altered." (PMID 41035784, 2025). "The VWF:Ag/ADAMTS13:AC increased according to the progression of ACLF in patients with cirrhosis and predicted prognosis in patients with cirrhosis with ACLF." (PMID 36829443, 2023). "The results of our study show that as cirrhosis progressed, ADAMTS13:AC levels gradually decreased, while VWF:Ag levels gradually increased." (PMID 35407443, 2022). "Patients with cirrhosis with high Et levels had lower and higher ADAMTS13:AC and VWF:Ag levels, respectively, than those with low Et levels." (PMID 35407443, 2022). "Therefore, whether levels of active VWF are truly increased in cirrhosis patients with HCC, and whether increased levels of VWF could have prognostic utility or become an additional therapeutic target, particularly in compensated cirrhosis, should be further explored." (PMID 33800224, 2021). "While patients with cirrhosis and mild-COVID exhibited comparable levels, ARDS-COVID patients had even higher VWF antigen levels, with most values being above the upper limit of quantification of the assay (>420%)." (PMID 34945736, 2021). "Elevated thrombin generation capacity and an unbalanced ratio between von Willebrand factor and its cleaving protein (ADAMTS13) have recently been described in cirrhosis." (PMID 33000389, 2020).
Cirrhosis (continued). "Cirrhosis produces “rebalanced hemostasis”, in which reductions in procoagulant factors are offset by decreases in endogenous anticoagulants and increases in factor VIII and von Willebrand factor." (PMID 41375590, 2025). "In cirrhosis, increased INR reflects decreased hepatic synthesis of procoagulant factors but does not account for concomitant decreases in natural anticoagulants and increases in prohemostatic mediators such as factor VIII and von Willebrand factor." (PMID 41375590, 2025). "Patients with cirrhosis are characterized by a clinical bleeding tendency and decreased levels of most procoagulant factors, except for elevated factor VIII and von Willebrand factor (vWF)." (PMID 36676794, 2023). "Therefore, a higher presence of these endothelial-derived MPs in the portal area, together with the increased levels of GAGs, vWF, and FVIII, all support the existence of the endothelial damage of the portal vein in patients with cirrhosis." (PMID 35160251, 2022). "In contrast, both PLVAP+ and VWF+ endothelial cells in the fibrosis and HCC samples were increased compared with the healthy cells, indicating that inflammation as well as angiogenesis happened in cirrhosis and malignant liver." (PMID 33532508, 2021). "ROC analysis showed that the area under the ROC curve of AFP, DCP, AFP-L3%, VEGF, VEGFR2, ADAMTS13:AC, VWF:Ag, and the VWF:Ag/ADAMTS13:AC ratio for the early diagnosis of HCC in patients with cirrhosis was 0.61, 0.58, 0.54, 0.74, 0.67, 0.59, 0.67, 0.63, and 0.73, respectively." (PMID 31638892, 2019). "vWF is cleaved by the protease ADAMTS13 (a disintegrin-like and metalloprotease with thrombospondin type 1 motif 13), which is mainly synthesized in the liver and found to be reduced in cirrhosis." (PMID 25397410, 2014). "Hypercoagulable states in cirrhosis have been attributed to decrease in the levels of natural anticoagulant proteins (protein C, protein S, and antithrombin III) and increase in factor VIII and von Willebrand factor levels." (PMID 24396346, 2013). "Taken together, it implies that PPIs among COL1A1, COL1A2, VWF and LUM may participate in the induction of cirrhosis and play roles in the progression from cirrhosis to HCC." (PMID 21526182, 2011). "Interestingly, changes in vWF levels in patients with decompensated cirrhosis treated with non-selective beta-blockers (NSBB) appeared to distinguish between those who benefit from NSBB therapy and have a favorable prognosis versus those with poor outcomes." (PMID 40429533, 2025). "In conclusion, while ABO blood type contributes to the variation in VWF levels in patients with early stage ACLD, its overall impact is considerably smaller than in the general population, and may vanish in patients with advanced cirrhosis." (PMID 32052552, 2020). "Levels of VWF were higher in patients with vs. without HCC (348 vs. 267; p = 0.006), particularly in compensated cirrhosis." (PMID 33800224, 2021). "Multiple studies have shown that vWF is not expressed by LSECs in healthy livers but is increased in LSECs during fibrosis in several animal models, for example after CCl4 treatment in mice and rats, and NASH with or without cirrhosis in rats." (PMID 34746184, 2021).